IL4 (interleukin 4)
Diseases named in the same sentence as IL4 in open-access papers (continued):
Sharing a sentence is not in itself a finding about the gene and the disease.
glioma (continued). "However, gliomas can acquire resistance to CSF-1R inhibition mediated by changes in the TME that lead to increased secretion of interleukin (IL)-4, a potent inducer of pro-tumor, alternatively activated TAMs, from CD8+ T cells and other cell types." (PMID 38254796, 2024). "Glioma cell have been illuminated to gang up on M2 macrophages which could be induced by IL4 and IL13 to invade the immune surveillance, especially in GBMs." (PMID 36434176, 2023). "We believe that our bioinformatic analysis might provide new insight for understanding the IL-4 involved mechanism of gliomas." (PMID 35203944, 2022). "Recently, we have reported that in the glioma microenvironment, levels of IL4, IL13, IL10, and TGFβ are increased by the IFNG response, which constitute a regulatory network of inflammatory responses and ultimately drives macrophages toward M2-type polarization." (PMID 35492352, 2022). "In our study, we focus on the cellular response to the IL-4 gene set from gene ontology in gliomas." (PMID 35203944, 2022). "Polymorphisms in the IL-4 receptor genes are reported to influence the glioma survival, which indicate that IL-4-induced inflammatory pathways might regulate the glioma development and prognosis." (PMID 35203944, 2022). "We believe that our bioinformatic analysis might provide a new insight for understanding the IL-4 involved mechanism of gliomas." (PMID 35203944, 2022). "In addition to its immune function, IL-4 produced by cancer cells is also reported to promote tumor proliferation and aggressiveness in glioma, bladder cancer, breast cancer and other epithelial tumors through STAT6 signal transduction pathways." (PMID 35203944, 2022). "Our IL-4-related signature can work as a molecular biomarker to classify glioma patients combined with current genetic biomarkers, which will be beneficial to predict survival more precisely and even can be used to predict clinical response to adjuvant therapies such as immunotherapy." (PMID 35203944, 2022). "Minimal differences were noted in IFNγ, TNFα, Granzyme B, and CD107B expression when comparing CD4+ T cells from glioma patients before and after M032 treatment; however, a significant reduction in IL-4 production between pre- and post-M032 treatment in peripheral blood CD4+ T cells was noted." (PMID 35342877, 2021). "OAd armed with IL-4 also showed potent anti-glioma immune activity in several glioma models." (PMID 33133514, 2020). "Additionally, IL-4 can affect the prognosis of gliomas, which are closely related to epilepsy, and improve cognitive function." (PMID 33013320, 2020). "Interestingly, pre-diagnostic serum levels of IL-4 and soluble IL-4RA have been later found inversely associated with gliomas and GBM in a nested case-control study including 487 glioma cases and 487 matched controls." (PMID 30909395, 2019). "However, OOS clearly inhibited the upregulation of M2 markers induced by IL4 incubation and, to a lesser extent, by glioma-CM, suggesting that OOS has a direct effect on these tumor inflammatory cells." (PMID 31467641, 2019). "Although we cannot discard such indirect effect, our results in vitro clearly indicate that OOS affects macrophage polarization in a direct way, reducing the expression of M2 markers in response to a classical inducer like IL4 but also in response to glioma-CM." (PMID 31467641, 2019). "IL-4 has a wide rang of application in immunotherapy against bacterial infections (e.g. Borrelia burgdorferi infection), parasitic infections (e.g. Schistosoma japonicum infection) and even cancer (e.g. malignant astrocytoma, glioma, glioblastoma and )." (PMID 23493491, 2011). "This study further compares microglial cells with other macrophage subsets, but the exact mechanism by which BV2 microglia and IL‐4‐treated BMDMs facilitate glioma cluster formation, in contrast to other macrophage subsets, remains unknown and warrants further investigation." (PMID 40747560, 2025).
glioma (continued). "Thus, as IL-4 induces a similar response in intractable epilepsy and glioma, IL-4/IL4R-STAT6 may be a potential therapeutic target for glioma-related epilepsy but requires future studies." (PMID 33013320, 2020). "Furthermore, it must be considered that IL-4, a classical type 2 cytokine, may induce type 1 immunity, increasing survival of glioma-bearing mice and decreasing tumorigenicity of sarcoma cell in vivo." (PMID 30813636, 2019). "However, the soluble receptor, sIL4RA, modulates IL4 so the mechanism by which this interaction would increase glioma risk more than 20 years before diagnosis is not apparent." (PMID 28594935, 2017). "One goal of the present study was to determine whether we would identify additional associations between individual prediagnostic serum cytokines and subsequent diagnosis of glioma and, if so, whether the previously observed interaction between IL4 and sIL4RA would persist in their presence." (PMID 28594935, 2017). "But in glioma tissues, there is obviously predominant expression of Th2 type cytokines, it may result tumor cells escape from immune response, so the abnormal secretion of IL-4, IL-10 and IL-13 may play an important role in the occurring and developing of human glioma." (PMID 23663500, 2013). "IL-4, IL-8, MMP-9 and PCNA promote glioma survival by inducing TAM immunosuppression, angiogenesis, glioma cell proliferation and clonogenic potential, and DNA replication and repair, respectively." (PMID 41034696, 2025). "In contrast, levels of IL-4, IFN-α, IFN-γ, IL-6, TNF-α, CCL4, P-cadherin, TRAIL, CCL11, and VEGF were significantly higher in serum than in CSF for both glioma and brain inflammation groups." (PMID 39364412, 2024). "The levels of serum factors IL-4, IFN-α, IFN-γ, IL-6, TNF-α, CCL4, CCL11, and VEGF were found to be significantly higher in gliomas compared with inflammatory diseases of the central nervous system (p < 0.05)." (PMID 39364412, 2024). "However, the role of cellular response to IL-4 in glioma development remains unclear." (PMID 35203944, 2022). "We found that the macro index performed better in predicting macrophages induced by IL13, IL4, and HDL, with similar efficiency between glioma groups." (PMID 36159811, 2022). "qRT-PCR assay demonstrated the upregulation of TNF-α, IL-2, IL-3, and IL-4 expression, whereas the downregulation of IL-12 expression in HK2-knockdown glioma cells, suggesting that HK2 is essential for glioma development through regulating immune infiltration." (PMID 35982398, 2022). "Different studies have reported on the importance of IL-4 and GMCSF in glioma development and/or progression, showing an enhanced risk and worse outcome of GBM for people that carry certain polymorphisms in IL-4R and STAT-6 gene loci." (PMID 34880868, 2021). "Glioma cells express multiple immune-suppressive cytokines such as transforming growth factor-beta (TGF-β), IL-10, IL-4, IL-6, and IL-13, all of which interfere directly or indirectly with anti-glioma immune response." (PMID 34084145, 2021). "So we could speculate that these differences might reflect a failed attempt by the mice to control the glioma by increasing tumor-suppressive Vγ4Vδ4+ cells that can be stimulated to produce IL-17, and decreasing tumor-promoting Vγ1Vδ6.3+ cells that can be stimulated to produce IL-4." (PMID 25955158, 2015). "The average frequency of Th17 that co-expressed IFN-γ, FoxP3 and IL-4 increased from 0%, 0%, and 0% in PBS-brains to 10±4%, 22±5% and 4±3%, in glioma brains, respectively." (PMID 21060663, 2010). "IL‐4‐treated BMDMs promote glioma clustering, unlike LPS‐treated BMDMs, suggesting that tumor‐associated BV2 cells were driven to an anti‐inflammatory phenotype that restricts proliferation while preserving antitumor immunity." (PMID 40747560, 2025).
glioma (continued). "An investigation into glioma patients reported a positive correlation between serum soluble α-Klotho (sαKlotho) levels and IL-6 (p = 0.0347), along with other biomarkers such as VEGF, fractalkine, IFN-γ, GDNF, IL-4, and IL-13." (PMID 40426990, 2025). "In glioma stem cells (GSCs), STAT3 activation leads to increased secretion of macrophage inhibitory cytokine-1 (MIC-1), IL-10, IL-4, and transforming growth factor β (TGF-β), which inhibit the phagocytic activity of macrophages and induce them to become immunosuppressive." (PMID 38254796, 2024). "It was observed that LPS/IFN‐γ MVs, but not Exos, inhibited the migration of glioma cell in vitro, while the IL‐4 MVs, and not Exos, promoted glioma cells’ migration." (PMID 33898169, 2021). "In contrast, expression of IL-4, another important cytokine that regulates Mφ and T-cell functions similar to IL-6, did not correlate with CD40 expression in patients with GBM or all grades of glioma." (PMID 34103524, 2021). "Admittedly, there are other known cytokines that activate STAT3, e.g. IL-4 and -13, and therefore the dependence of our results on IL-6 effect alone is not confirmed as of yet, as it requires validation in other glioma cell lines outside of the ones we tested." (PMID 31361777, 2019). "Interestingly, some Th17 cells present in mouse glioma co-expressed the Th1 and Th2 lineage markers, IFN-γ and IL-4, respectively, but predominantly co-expressed the Treg lineage marker FoxP3." (PMID 21060663, 2010). "We have previously observed that none of the solid tumour cell lines including glioma cell lines secrete IL-4." (PMID 11870521, 2002). "Notably, there was overexpression of various cytokines, including IL-1β, IL-4, IL-6, IL-8, IL-10, TGF-β and TNF in the patient cohort, which was unsurprising given that these cytokines serve primarily immunosuppressive roles in the glioma microenvironment." (PMID 41034696, 2025). "On the other hand, the inverse associations between P2X7R expression and IL-4, IL-8, MMP-9 and PCNA were not in line with previous speculations of P2X7R and glioma promotion." (PMID 41034696, 2025). "Therefore, to further confirm our hypothesis, we next examined the expression of several key inflammatories and immune modulators, including TNF-α, IL-2, IL-3, IL-4, and IL-12, in HK2-silenced T98 and GBM1 glioma cells." (PMID 35982398, 2022). "One week after engrafting glioma cells to the brain of mice, the LPS/IFN‐γ MVs were infused in the tumor region, and one week after, a significant reduction of tumor size was observed, compared to the infusion of IL‐4 MVs that resulted in the increased tumor size." (PMID 33898169, 2021). "Of note, although arginase 1 gene expression was significantly reduced in CD11b+ cells isolated from glioma-bearing mice upon sEVs treatment, the result was not confirmed on IL4-stimulated microglial cells or by the release of NO by BV2 cells, suggesting the need of further investigations." (PMID 34440835, 2021). "After migrating into the glioma environment, TAMs tend to possess the M2 phenotype, and their differentiation is driven by the secretion of immunosuppressive factors, including CSF-1, CCL2, IL-4, IL-6, IL-10, and transforming growth factor (TGF- β), from tumor cells." (PMID 30619286, 2018). "Instead we demonstrate by immunoprecipitation experiments and mass spectrometry that the antigen recognized by the B-D13 antibody following cytokine stimulation is VCAM-1, and that VCAM-1, but not IL13Rα2, is induced on glioma cells by TNF alone or in combination with IL-13 or IL-4." (PMID 24787244, 2014). "Besides, previously results showed that IL4, IL4R and IL13 genes may play an important role in glioma survival." (PMID 23663500, 2013). "As IL-4 promotes maturation and IL-12 production of DCs, we subsequently developed another trial for patients with newly diagnosed malignant glioma, using TFG-hIL4-Neo-TK-transfected fibroblasts and type-1-promoting DCs loaded with autologous glioma lysate (UPCI 99-111)." (PMID 18093335, 2007).
glioma (continued). "In order to analyze if the changes in macrophage polarization induced by OOS could affect secondarily glioma cells, we incubated GBM1 cells on top of macrophages that had been previously polarized by IL4, in the presence or in the absence of OOS." (PMID 31467641, 2019).
liver fibrosis (75 papers, 2008 to 2025). "In a group of patients with advanced liver fibrosis, liver steatosis was linked with lower serum concentrations of IL-4, IL-5, IL-9, IL-10, IL-13 and IL-22." (PMID 39200991, 2024). "A study on 611 patients with Schistosoma japonicum infection confirmed the association of Th2 cytokines, including IL-4 and IL-13, with liver fibrosis." (PMID 36982747, 2023). "The important roles of IL-4 and Th2 cells in bacterial infection-associated hepatic fibrosis have long been recognized." (PMID 32708044, 2020). "Our findings also confirmed that CsTPs initiated Th2-cell skewing immune responses to markedly elevate the production of IL-13 and IL-4 which are closely associated with the generation of liver fibrosis." (PMID 29505573, 2018). "We found that the serum IP-10 levels were positively correlated with the severity of liver fibrosis, whereas the IFN-γ/IL-4 ratio was negatively associated with the progression of hepatic fibrosis." (PMID 28067328, 2017). "But Th2 cytokines such as IL-4, IL-10 and IL-13 are associated with the aggravated pathological injuries and our previous study showed that the imbalanced Treg/Th17 may play a role in the formation of liver fibrosis." (PMID 28151995, 2017). "Given that previous findings have associated Th2 responses with enhanced hepatic fibrosis, the significantly elevated Th2 cytokines IL-4 and IL-5 in co-infected patients may be a major reason that co-infected patients tend to have accelerated progression of HCV." (PMID 23593207, 2013). "We then focused on the effect of IL-34 + IL-4 Mf in the formation of hepatic fibrosis in the TAA model." (PMID 39856797, 2025). "The Th2-derived cytokines IL-4 and IL-13 activate hepatic stellate cells, driving excessive extracellular matrix (ECM) deposition—a hallmark of hepatic fibrosis." (PMID 41154658, 2025). "In this experiment, IL-34 + IL-4-induced Mf showed the strongest potential to treat liver fibrosis among the Mfs examined." (PMID 39856797, 2025). "In contrast, the IL-34 + IL-4 Mfs significantly suppressed liver fibrosis compared to the saline or IL-34 alone group." (PMID 39856797, 2025). "In this study, we clearly indicated that IL-34-induced Mf, particularly when alternatively activated by the addition of IL-4, significantly ameliorated liver fibrosis in mouse models." (PMID 39856797, 2025). "It is therefore likely that human IL-34 + IL-4-induced Mfs are as effective against liver fibrosis as in mice." (PMID 39856797, 2025). "Interleukin 34-induced macrophages, particularly when additionally stimulated with interleukin 4, significantly ameliorated the liver fibrosis." (PMID 39856797, 2025). "In the liver, IL-4 plays a dual role in liver fibrosis by inducing KCs to transform into multinucleated giant cells, stimulating the proliferation of HSCs, upregulating PPARγ, and regulating macrophage polarization." (PMID 39995661, 2025). "In a subgroup of patients with advanced liver fibrosis, SLD was linked with lower serum concentrations of IL-4, IL-5, IL-9, IL-10, IL-13 and IL-22 and higher concentrations of HGH and VEGF." (PMID 39200991, 2024). "Previous research has demonstrated that LPS/IFN‐γ‐treated macrophages are more effective in hepatic fibrosis therapy than untreated or IL‐4‐treated macrophages, indicating that more defined macrophages result in more effective therapy." (PMID 38247166, 2024). "Remarkably, the liver fibrosis mice treated with vitamin D resulted in a substantial reduction in the levels of the tested cytokines: IL-1β (2.2-fold), IL-4 (1.9-fold), IL-6 (8-fold), OPN (1.45-fold), and TNF-α (1.7-fold) compared to CCl4 alone." (PMID 39654627, 2024). "Hepatic granulomatous inflammation, hepatic fibrosis and IL-4 production in the liver was significantly reduced in mice lacking cysLTR1 during chronic schistosomiasis, while reduced liver pathology was observed during acute schistosomiasis." (PMID 38840916, 2024).
liver fibrosis (continued). "Our current study confirmed the anti-inflammatory effects of vitamin D supplementation on mice with liver fibrosis through reductions in IL-1β, IL-4, IL-6, and TNFα in addition to OPN." (PMID 39654627, 2024). "IL-4 and IL-6 protect against hepatic fibrosis, IL-4 through secretion of matrix metalloproteinase-12 (MMP-12), and IL-6 through the promotion of proliferation/survival of HSCs." (PMID 38251375, 2024). "IL-6, TNF-α and IL-4 are important cytokines involved in liver inflammation, liver injury and liver fibrosis." (PMID 36693049, 2023). "In the present study, the productions of IL-6, TNF-α and IL-4 were significantly elevated in C. sinensis-induced liver fibrosis, which is consistent with previous studies." (PMID 36693049, 2023). "Significant upregulation of IL-4 was detected in the fibrotic livers of Schistosoma mansoni-infected baboons, while blockade of IL-4 resulted in significantly less hepatic fibrosis in mice infected with Schistosoma mansoni." (PMID 36671504, 2023). "Studies pointed out that IL-4 and IL-13 is capable of protecting against ischemia/reperfusion and inhibits inflammation; subsequently, it prevents hepatic fibrosis in drug-induced liver injuries through STAT6 activation." (PMID 36671504, 2023). "The elevated expression of IL-33 is associated with the activation of IL-33 receptor (IL-33R) through ST2 signaling, leading to the increased production of IL-4 and IL-13 with the increase in liver fibrosis." (PMID 36271450, 2022). "In OB, interleukin-4 and interleukin-13 indicated via the IL-4R modulates adipose tissue lipolysis, insulin sensitivity, and liver fibrosis." (PMID 36314741, 2022). "CD4+ T cells activity mediates the progression of liver fibrosis by intrinsic apoptosis, by secreting signature cytokines IL-4, IL-10, and IFN-γ, and by stimulating other immune cells such as NK cells." (PMID 35903097, 2022). "NKT cells secrete IL-4 to recruit and promote accumulation of neutrophils, thus enhancing hepatitis and liver fibrosis." (PMID 36389715, 2022). "Meanwhile, IL4 and Il-13 enhance macrophage differentiation to M2 cells which promote the synthesis of liver collagen and subsequent hepatic fibrosis." (PMID 35576078, 2022). "Th2 cytokines such as IL-4 and IL-13 promote hepatic stellate cell activation and accelerate the process of liver fibrosis." (PMID 34190168, 2021). "At the genus level, liver fibrosis and IL-4 which indicated Th2 response had higher correlation with Odoribacter, Alloprevotella, and Escherichia-Shigella." (PMID 32295161, 2020). "The imbalance of IFN-γ-producing T helper (Th1) cells and IL-4-producing T helper (Th2) cells, which are the anti-fibrotic and pro-fibrotic Th subsets, respectively, also promotes liver fibrosis." (PMID 33178216, 2020). "The samples fermented at liver fibrosis and IL-4 were similar to each other, indicating that there were more microorganisms with similar community structures and a high correlation between these two environmental factors." (PMID 32295161, 2020). "Bacteroidetes were positively related with liver fibrosis and IL-4, but negatively related with IFN-γ." (PMID 32295161, 2020). "At the phylum level, the RDA result of samples demonstrated that Epsilonbacteraeota, Proteobacteria, and Verrucomicrobia were positively related with liver fibrosis, IL-4 and IFN-γ." (PMID 32295161, 2020). "Our findings also illustrated that CsTPs endowed host with the capacity to facilitate a Th2 cytokine production including IL-13 and IL-4 in vitro and vivo, thus possibly promoting the formation and development of liver fibrosis." (PMID 29505573, 2018). "The aim of this study was to evaluate the predictive value of the IP-10 level alone or in combination with the IFN-γ/IL-4 ratio for liver fibrosis progression in patients with chronic HBV infection." (PMID 28067328, 2017).